USP5 (ubiquitin specific peptidase 5)
Description:
Deubiquitinating enzyme that participates in a wide range of cellular processes by specifically cleaving isopeptide bonds between ubiquitin and substrate proteins or ubiquitin itself. Affects thereby important cellular signaling pathways such as NF-kappa-B, Wnt/beta-catenin, and cytokine production by regulating ubiquitin-dependent protein degradation. Participates in the activation of the Wnt signaling pathway by promoting FOXM1 deubiquitination and stabilization that induces the recruitment of beta-catenin to Wnt target gene promoter. Regulates the assembly and disassembly of heat-induced stress granules by mediating the hydrolysis of unanchored ubiquitin chains. Promotes lipopolysaccharide-induced apoptosis and inflammatory response by stabilizing the TXNIP protein. Affects T-cell biology by stabilizing the inhibitory receptor on T-cells PDC1. Acts as a negative regulator of autophagy by regulating ULK1 at both protein and mRNA levels. Acts also as a negative regulator of type I interferon production by simultaneously removing both 'Lys-48'-linked unanchored and 'Lys-63'-linked anchored polyubiquitin chains on the transcription factor IRF3. Modulates the stability of DNA mismatch repair protein MLH1 and counteracts the effect of the ubiquitin ligase UBR4. Upon activation by insulin, it gets phosphorylated through mTORC1-mediated phosphorylation to enhance YTHDF1 stability by removing 'Lys-11'-linked polyubiquitination. May also deubiquitinate other substrates such as the calcium channel CACNA1H (By similarity).
Synonyms: ISOT
Tractability: Small molecule: a structure with a bound ligand is known; a high-quality ligand is known; it has a high-quality binding pocket. PROTAC: UniProt records ubiquitination sites on it; ubiquitination databases record sites on it; its protein half-life has been measured; a small molecule that binds it is known.
Target class: Cysteine protease; Cysteine protease CA clan; Protease; Enzyme; Cysteine protease C19 family
Gene: Protein-coding gene on chromosome 12 (6,852,122 to 6,866,632, forward strand). Ensembl gene ENSG00000111667.
Subcellular location: Cytoplasm; Cytoplasm, Stress granule; Nucleus
Subcellular location (Human Protein Atlas): Cytosol; Nucleoplasm
Pathways (Reactome):
Metabolism of proteins: Synthesis of active ubiquitin: roles of E1 and E2 enzymes; Ub-specific processing proteases
Gene Ontology:
Molecular function: cysteine-type deubiquitinase activity; deubiquitinase activity; protein binding; ubiquitin binding; cysteine-type endopeptidase activity; zinc ion binding
Biological process: negative regulation of proteasomal ubiquitin-dependent protein catabolic process; negative regulation of T cell mediated immune response to tumor cell; negative regulation of ubiquitin-dependent protein catabolic process; positive regulation of proteasomal ubiquitin-dependent protein catabolic process; protein K48-linked deubiquitination; protein deubiquitination; protein ubiquitination; positive regulation of proteasomal protein catabolic process
Cellular component: cytoplasm; nucleus; cytosol; lysosome; cytoplasmic stress granule
Genetic constraint (gnomAD): Loss-of-function variants: 24 observed, 102.54 expected, observed/expected ratio (o/e) 0.23, 90% interval 0.17 to 0.33. The upper end of that interval is the gene's LOEUF score, 0.33, which puts it in group 1 of 6, group 1 being the genes least tolerant of losing a copy. Missense variants: 753 observed, 1,157.6 expected, observed/expected ratio (o/e) 0.65, 90% interval 0.61 to 0.69. Synonymous variants: 460 observed, 453.85 expected, observed/expected ratio (o/e) 1.01, 90% interval 0.94 to 1.1.
Homologues: Orthologues: chimpanzee USP5 (100% identical), guinea pig USP5 (99% identical), dog USP5 (99% identical), mouse Usp5 (98% identical), rat Usp5 (98% identical), macaque USP5 (97% identical), rabbit USP5 (89% identical), pig USP5 (89% identical), tropical clawed frog usp5 (76% identical), zebrafish usp5 (68% identical). Paralogues in human: USP13 (60% identical), USP24 (16% identical), USP32 (15% identical), USP4 (14% identical), USP9X (14% identical), USP9Y (13% identical), USP15 (13% identical), USP11 (13% identical), USP35 (13% identical), USP8 (13% identical), USP10 (12% identical), USP31 (12% identical), and 59 more.
Diseases named in the same sentence as USP5 in open-access papers:
USP5 is named in the same sentence as 73 diseases in open-access papers, as found by Europe PMC text mining. Sharing a sentence is not in itself a finding about the gene and the disease. The quoted sentences say what the papers report.
hepatocellular carcinoma (21 papers, 2017 to 2025). A malignant tumor that arises from hepatocytes. "Several studies have demonstrated that USP5 associated with malignancy and pathological progression in hepatocellular carcinoma, colorectal and non-small cell lung cancer." (PMID 38229092, 2024). "Increased USP5 levels have been associated with tumorigenesis in human glioblastoma, melanoma, and hepatocellular carcinoma." (PMID 33658627, 2021). "Increased ubiquitin-specific protease 5 (USP5) has been associated with tumorigenesis of malignancy including pancreatic cancer, melanoma, non-small-cell lung cancer, and hepatocellular carcinoma." (PMID 32214906, 2020). "METTL5 regulates hepatocellular carcinoma (HCC) proliferation through numerous pro-oncogenic USP5-c-Myc signaling cascades." (PMID 39289775, 2024). "In hepatocellular carcinoma, USP5 interacts with and stabilizes SLUG to promote the EMT and malignant progression of cancer." (PMID 38217030, 2024). "USP5 also plays an oncogenic role in a variety of cancers, including glioblastoma, lung cancer, hepatocellular carcinoma (HCC), ovarian and pancreatic cancer." (PMID 37607937, 2023). "The antitumor capability of formononetin was also revealed in the treatment of hepatocellular carcinoma through its interaction with ubiquitin-specific protease 5 (USP5)." (PMID 37197593, 2023). "USP5 have been reported as an oncoprotein in diverse cancers including myeloma 4, non-small cell lung cancer 5, hepatocellular carcinoma 6, colorectal cancer 7, ovarian cancer 8 and pancreatic cancer." (PMID 33123271, 2020). "It was found that Usp5 was significantly upregulated in hepatocellular carcinoma (HCC) cells and most clinical specimens." (PMID 28881591, 2017). "Treatment of degrasyn targeting USP5 has an obvious effect on hepatocellular carcinoma (HCC)." (PMID 37492786, 2023). "Moreover, USP5 was recently shown to play a critical role in epithelial-mesenchymal transition (EMT) of hepatocellular carcinoma by regulating levels of the transcription factor, SLUG." (PMID 35895711, 2022). "USP5 expression was found increased in glioblastoma, melanoma, and hepatocellular carcinoma." (PMID 32214906, 2020). "Moreover, USP5 intervention by shRNA knockdown has been reported to prevent the metastasis of hepatocellular carcinoma in vivo." (PMID 32477134, 2020). "USP5 expression is up-regulated in hepatocellular carcinoma and pancreatic cancer." (PMID 31727867, 2019). "In hepatocellular carcinoma (HCC) and colorectal cancer (CRC), USP5 is highly expressed and closely associated with malignancy and pathological progression." (PMID 38229092, 2024). "Recently, USP5 has been show to promote epithelial–mesenchymal transition and metastasis through stabilizing SLUG protein level in hepatocellular carcinoma." (PMID 34741014, 2021). "It has been reported that USP5 is highly expressed and stabilizes SLUG, which is the key transcription factor of EMT, promoting malignant progression in hepatocellular carcinoma cells." (PMID 32477134, 2020). "Furthermore, it has been demonstrated that USP5 acts oncogenic roles in glioblastoma, hepatocellular carcinoma (HCC), melanoma and pancreatic cancer." (PMID 31727867, 2019).
hepatocellular carcinoma (continued). "USP5 significantly elevated METTL3 expression and reduced METTL3 ubiquitination in hepatoma cells." (PMID 40651967, 2025). "USP5 targets the transcription factor SLUG and then induces EMT in hepatocellular carcinoma cells." (PMID 32477134, 2020). "Here, we found that ubiquitin‐specific protease 5 (USP5) is regarded as a bona fide DUB of lymphoid‐specific helicase (LSH), a DNA methylation repressor, in hepatocellular carcinoma (HCC)." (PMID 37492786, 2023).
melanoma (17 papers, 2014 to 2025). A malignant, usually aggressive tumor composed of atypical, neoplastic melanocytes. "In line with this, the loss of USP5 in yeast and in a human melanoma cell line led to the accumulation of free polyubiquitin chains." (PMID 25806519, 2015). "We first examined effects of USP5 knock down (KD) in A375 (sensitive) melanoma cells treated with TRAIL." (PMID 31645897, 2019). "Initially, we used specific knockdown (KD) of this subset of DUBs to examine their role in melanoma and other resistant cells and determined that USP5 KD -sensitizes cells to TRAIL." (PMID 31645897, 2019). "A small molecule DUB inhibitor (EOAI3402143) phenocopied the FAS induction and apoptotic sensitization of Usp5 knockdown and fully blocked melanoma tumor growth in mice." (PMID 24980819, 2014). "In BRAF mutant melanoma cells, Usp5 activity was suppressed by BRAF inhibitor (vemurafenib) in sensitive but not in acquired or intrinsically resistant cells." (PMID 24980819, 2014). "The enriched macrophages and CD3+CD8+ T cells were also observed in Usp5-depleted B16 melanoma." (PMID 41321309, 2025). "In addition, both systematic Ifnar1 blocking and KO of tumor cell–intrinsic Ifnar1 reversed the growth retardation of Usp5-depleted murine B16 melanomas." (PMID 41321309, 2025). "To explore whether and how USP5 interrupts antitumor immunity, we employed the B16 murine melanoma and CT26 and MC38 murine colon cancer models." (PMID 41321309, 2025). "However, contrary to the melanoma model, where downregulation of USP5 leads to cell-cycle arrest in the G2/M phase as reported by Potu et." (PMID 29029505, 2017). "For Usp5, it has been demonstrated to play a significant role in glioblastoma and melanoma." (PMID 28881591, 2017). "Overexpression of Usp5 nearly doubled the rate of melanoma growth when compared to control cells." (PMID 24980819, 2014). "Based on the scRNA-Seq data of NPC, melanoma, and colon cancer, we found that USP5 was dominantly expressed in tumor cells, indicating that tumor-intrinsic USP5 might inhibit IFN-I response and CXCL9hi macrophage–CD8+ T cell antitumor immunity." (PMID 41321309, 2025). "Thus, targeting USP5 offers a potential therapeutic strategy for BRAF inhibitor-resistant melanoma." (PMID 36694209, 2023). "Therefore, we further examined whether inhibition of caspase-8 could block USP5 cleavage in A375 melanoma cells." (PMID 31645897, 2019).
melanoma (continued). "However, we have been unable to detect changes in Usp5 phosphorylation in vemurafenib-treated melanoma or BRAFV600E over-expressing cells, suggesting other mechanisms of activation, (i.e. allosteric) may be operant." (PMID 24980819, 2014). "HA blotting demonstrated that TRAIL exposure altered USP5 activity and induced its cleavage in TRAIL-sensitive melanoma A375 cells." (PMID 31645897, 2019). "Usp5 knockdown overcame acquired vemurafenib resistance and sensitized BRAF and NRAS mutant melanoma cells to apoptosis initiated by MEK inhibitor, cytokines or DNA-damaging agents." (PMID 24980819, 2014). "Moreover, USP5 deprivation reversed resistance to vemurafenib and sensitized BRAF-mutant melanoma cells to apoptosis initiated by BRAF inhibitors." (PMID 36694209, 2023). "USP5 KD increased apoptotic response (Bid and PARP cleavage) to TRAIL in melanoma cells." (PMID 31645897, 2019). "Two mutant and two non-mutant BRAF melanoma cell lines were subjected to Usp5 KD and their growth kinetics were assessed over four days after plating equal numbers of initiating cells." (PMID 24980819, 2014).
pancreatic cancer (13 papers, 2017 to 2023). "It has been reported that USP5 overexpressed in many tumors and implicated in its progression, including pancreatic cancer, breast cancer, and glioblastoma." (PMID 36611139, 2023). "On this regard the ubiquitin-specific protease 5 (USP5) has been recently associated with pancreatic cancer tumorigenesis and progression for its role in extending the half-life of FOXM1 by reducing its endogenous ubiquitination." (PMID 35241126, 2022). "Univariate and multivariate analyses demonstrated that high USP5 expression is an independent risk factor for pancreatic cancer." (PMID 33123271, 2020). "Kaplan-Meier survival analysis was performed to explore the association between USP5 expression and survival time in pancreatic cancer patients." (PMID 33123271, 2020). "Loss of USP5 leads to accumulation of DNA damage in pancreatic cancer cells as evidenced by elevated levels of phos.H2A.X." (PMID 29029505, 2017). "Indeed, USP family genes have been proposed as biomarkers in different malignancies, and further research will have to show if USP5 may be suitable as a novel diagnostic marker and/or novel therapeutic target in pancreatic cancer." (PMID 29029505, 2017). "For example, overexpression of USP5 was shown to stabilise FoxM1, a protein with a key role in tumorigenesis and progression of pancreatic cancers." (PMID 35895711, 2022). "USP5 promotes tumorigenesis of pancreatic cancer cells by stabilising the FoxM1 protein, which is a substrate of FBXW7." (PMID 33658627, 2021). "In pancreatic carcinoma cells, knockdown of USP5 exhibited growth inhibition effects by suppressing cell cycle G1 to S transition, which was mediated by downregulating the cell cycle regulators." (PMID 34483932, 2021). "We also confirmed that USP5 mRNA was highly expressed in pancreatic cancer cell lines compared with normal pancreatic cells." (PMID 33123271, 2020). "Both mRNA and protein expressions of USP5 were substantially increased in four pancreatic cancer cells than in HPDE 6C7 cells." (PMID 31845546, 2020). "The USP5 mRNA level was detected in normal pancreatic cell and multiple pancreatic cancer cells, showing that USP5 mRNA expression was significantly increased in metastasis cells than primary cancer cells." (PMID 33123271, 2020). "In this study, we reported that USP5 is highly expressed in pancreatic cancer, especially in metastasis." (PMID 33123271, 2020). "The protein expression of WT1 was measured in pancreatic cancer cells, which were transduced with specific shRNAs for USP5, USP9x or USP14, respectively." (PMID 31845546, 2020). "RT-qPCR were carried out to quantitate the mRNA expression levels of USP5 in pancreatic cancer cell lines." (PMID 33123271, 2020). "USP5 has been reported to play vital roles in tumor progression in various cancers, including pancreatic cancer, liver cancer, and colorectal cancer." (PMID 32477134, 2020). "USP5 overexpression is critical in both pancreatic cancer progression and metastasis via enhancing STAT3 signaling." (PMID 33123271, 2020). "To further investigate how USP5 affect pancreatic cancer migration and invasion, we overexpressed USP5 in Panc1 cells and knockdown USP5 in AsPC1 cells." (PMID 33123271, 2020). "We also found that increased USP5 expression is related to pancreatic cancer in both proliferation and metastasis in vitro." (PMID 33123271, 2020). "In the public GEPIA database, we also found that USP5 expression was significantly higher in pancreatic cancer tissue than in normal tissue." (PMID 33123271, 2020). "To further identify the role of USP5 in pancreatic cancer, we knockdown the expression of USP5 in AsPC1 cells by shRNA." (PMID 33123271, 2020). "We detected USP5 expression in 11 pairs of primary pancreatic tumors and lymph node metastasis tissues." (PMID 33123271, 2020). "In pancreatic cancer, knockdown of USP5 up-regulated p27, attenuated G1/S phase transition, and inhibited cell proliferation." (PMID 31727867, 2019).